APOE (apolipoprotein E)
Diseases named in the same sentence as APOE in open-access papers (continued):
Sharing a sentence is not in itself a finding about the gene and the disease.
Alzheimer disease (continued). "The study revealed a significant increase in brain ApoE levels in the ALZ group and ALZ+TYM group, marking the first study to investigate the impact of thymol on ApoE levels in Alzheimer’s disease." (PMID 38665779, 2024). "Within APOE‐ε4 non‐carriers, the highest PRS quintile predicted the Alzheimer's disease 72% of the time compared to 14% for the lowest quintile." (PMID 36946865, 2023). "Results of logistic regression for vascular dementia with sex, APOE ε4 status, cardiovascular problems at baseline, ethnicity and Townsend Deprivation Index (TDI) at baseline, using the Alzheimer disease category as reference." (PMID 37467176, 2023). "Direct RXR and LXR agonists raise CNS apoE lipidation and HDL cholesterol concentrations in plasma and improve cognition in animal models of Alzheimer’s disease." (PMID 36979690, 2023). "We obtained patient data from the Alzheimer’s Disease Neuroimaging Initiative (ADNI) database, including clinical information, neuropsychological test results, neuroimaging-derived biomarkers, and APOE-ε4 gene statuses." (PMID 37491248, 2023). "However, different from Alzheimer's disease with a well-known risk SNP APOE rs429358, there were no consistent gene hypotheses for the pathogenesis of MDD." (PMID 36937715, 2023). "Within discordant sibships where both siblings were APOE‐ε4 carriers, the highest PRS quintile predicted Alzheimer's disease 85% of the time compared to 35% in the lowest quintile." (PMID 36946865, 2023). "Alternatively, Alzheimer’s disease can be modeled by exposing NVU-on-a-chip models to proteins involved in Alzheimer’s pathology, such as phosphorylated Tau, amyloid β (Aβ), or apolipoprotein E (APOE)." (PMID 38008744, 2023). "For example, in Alzheimer’s disease, DAM have been characterized by the upregulation of genes such as apolipoprotein E (APOE) and triggering receptor expressed on myeloid cells 2 (TREM2) while downregulating genes involved in synaptic function and homeostasis." (PMID 37511539, 2023). "Overview of studies illustrating epigenetic signatures of apolipoprotein E gene (APOE) in aging and Alzheimer’s disease (AD)." (PMID 38132357, 2023). "Nevertheless, β-amyloid (Aβ), apolipoprotein E (APOE), and protein tau are still considered the substantial elements which contribute to Alzheimer’s disease pathophysiology." (PMID 35566501, 2022). "The objective was to determine the influence of the APOE genotype on HDL function and size in the context of Alzheimer’s disease." (PMID 35884800, 2022). "In the pathogenesis of Alzheimer’s disease, the interplay between BDNF and the ApoE genotype is crucial." (PMID 35743271, 2022). "Despite the lack of information about GJA1 in leprosy, this has been described in neural impairment, like in the pathogenesis of Alzheimer's disease, where GJA1 downregulation leads to reduced levels of ApoE." (PMID 35492305, 2022). "The links between lipids metabolism and Alzheimer’s disease reveals apolipoprotein E as a key factor, and these studies demonstrate that upregulation of LDL-R can lead to a reduction in ApoE and alleviation of AD pathologies." (PMID 35886936, 2022). "Multimarker models were developed using 10 protein biomarkers and apolipoprotein E genotypes for amyloid beta and 10 biomarkers with Korean Mini-Mental Status Examination (K-MMSE) score for predicting Alzheimer disease progression." (PMID 35075217, 2022). "In the dementia and HC data set, the proportion of APOE ε4 carriers (APOE genotype was missing for oneparticipant) and CDR Sum of Boxes was significantly higher (P < 0.05) in the Dem-Alzheimer's disease group compared with those with normal cognition." (PMID 35800899, 2022). "Finally, the subgroup analyses showed that neither the recruitment wave nor the presence of risk factor(s) for Alzheimer disease (apolipoprotein E ε4 genotype, brain amyloid positivity, familial history of dementia, or presence of at least 1 of these risk factors) affected the results." (PMID 36215061, 2022).
Alzheimer disease (continued). "Notably, apolipoprotein E (APOE), which is directly connected to the products of three other members of this network, is known for its anti-angiogenic functions and has been implicated in several diseases with racial disparity, including Alzheimer’s disease and age-related hearing loss." (PMID 33983985, 2021). "After testing interactions between DHA and APOE on brain volume, we investigated whether DHA and APOE interact to predict spatial navigation performance on a novel virtual reality diagnostic test for Alzheimer’s disease in an independent population of APOE genotyped adults (n = 46)." (PMID 34007965, 2021). "Combined Alzheimer's disease neuroimaging initiative (ADNI) and National Alzheimer's Coordinating Center (NACC) sample demographics organized by ethnicity and the APOE ε4 status." (PMID 33716715, 2021). "Further analyses indicated that the APOE-ε4ε4 haplotype carriers were less likely to participate in the MHQ and high genetic liability for Alzheimer’s disease lowered odds of participation in the FFQ, physical activity monitoring and the MHQ." (PMID 33563987, 2021). "Compared to the typical Alzheimer’s disease (AD) patients, our MCI patients were relatively younger; differences in age likely contributed to these diverging results on the effects of APOE-ε4 on cognitive performance." (PMID 33658917, 2021). "The epigenetic regulation is an important aspect of Alzheimer’s disease as the expression level of many key proteins such as APP, BACE1, Presenilins and ApoE are known to be under epigenetic regulation." (PMID 33962636, 2021). "During Alzheimer disease (AD), disease-associated microglia (DAM) and late-response microglia are defined by the expression of genes related to lipid metabolism and phagocytosis (ApoE, Lpl, Trem2, Tyrobp, Ctsd) and interferon response." (PMID 34540682, 2021). "Participants performed the Korean version of the Consortium to Establish a Registry for Alzheimer’s disease (CERAD-K), the clinical dementia rating (CDR), plasma oligomeric amyloid-β (OAβ) level tests, routine blood tests, ApoE genotype, and brain MRI." (PMID 32326061, 2020). "This may be due to higher predictive power of the polygenic score or indicate that APOE ɛ4 is specifically related to risk for Alzheimer’s disease through pathological processes that are not involved in normal aging, or impact later stages of the disease progression." (PMID 32709845, 2020). "Moreover, the traditional metric of semantic fluency (total number of items) has been shown to fail at distinguishing non-demented APOE e4 carriers (i.e., genetic risk for Alzheimer’s disease) from non-carriers, while an alternative item-level metric was able to distinguish these groups." (PMID 33091462, 2020). "To this end, we repeated the analysis of how Alzheimer’s disease PRS and APOE influence pathology, sequentially controlling for other neuropathology variables." (PMID 33376986, 2020). "In another study of individuals with SCD from the Alzheimer’s Disease Neuroimaging Initiative (ADNI) database, ApoE ɛ4 carriers with SCD showed higher levels of amyloid accumulation than noncarriers." (PMID 32962744, 2020). "The interaction between APOE and MAPT is known to play a crucial role in Alzheimer’s disease as APOE affects tau-mediated neurodegeneration." (PMID 31017923, 2019). "In addition, it has been shown that expression of apolipoprotein E, a major genetic risk factor for Alzheimer’s disease, or a lack of murine apolipoprotein E can lead to vascular dysfunction and BBB breakdown by activating the pro-inflammatory CypA-nuclear factor-κB-MMP9 pathway in pericytes." (PMID 31316352, 2019).
Alzheimer disease (continued). "The purpose of this study was to investigate the effects of aerobic training before and after the induction of Alzheimer’s disease on ABCA1 and APOE mRNA expression and the level of soluble Aβ1-42 in the hippocampus of male Wistar rats." (PMID 31168344, 2019). "Although apoE is considered as a key player in the pathogenesis of Alzheimer’s disease (AD) and CAA, the effects of apoE on the aggregation of Aβ in vitro and in vivo are controversial." (PMID 30691533, 2019). "Finally, genetic predisposition (such as having the APOE-4 gene, which may increase the risk of Alzheimer’s disease), and traffic-related exposure were not considered in our models." (PMID 31591354, 2019). "However, several authors argue that any association between APOE and cognitive decline is largely or entirely attributable to pre-clinical Alzheimer’s disease, and thus APOE may not play a role in non-pathogenic decline." (PMID 30339707, 2018). "Moreover, potential moderators such as perceived safety or aesthetics and genetic risk profiles (e.g., apolipoprotein E as a risk factor for Alzheimer’s disease) were not available, nor were individual-level confounders such as smoking and individual socioeconomic status." (PMID 29494513, 2018). "This resulted in a comparison between the young, Alzheimer's disease, Old PIB+ ApoE ε4+, and all other cognitively normal older subjects (i.e. “Other Old group”, N = 48)." (PMID 29527500, 2018). "The Young group differed profoundly from the Other Old group showing widespread reductions in correlation strength, but exhibited less extensive differences with the Alzheimer's disease group and the Old PIB+ ApoE ε4+ group." (PMID 29527500, 2018). "Since Reelin and apolipoprotein E, are ligands of ApoER2 and VLDLR, these receptors are of interest with respect to Alzheimer’s disease." (PMID 30304853, 2018). "We explore the effect of two Alzheimer's disease risk factors, amyloid-β and ApoE ε4 genotype, on metabolic brain networks in cognitively normal older adults (N = 64, ages 69–89) compared to young adults (N = 17, ages 20–30) and patients with Alzheimer's disease (N = 22, ages 69–89)." (PMID 29527500, 2018). "The cognitive and neural effects of the APOE gene have been subject to intense study in recent years, on the basis that carriers of the ε4 variant are at considerably higher risk of developing late onset Alzheimer’s disease (AD) and also show poorer cognitive ageing in non-clinical populations." (PMID 29856823, 2018). "Presenilin-1(PSEN-1) and Apolipoprotein E (APOE) genes areassociated with early and late onset of Alzheimer's disease, respectively." (PMID 28767121, 2017). "These turn out to be the primary and hot research topics, including “Alzheimer’s Disease”, “MCI”, “MRI”, “Biomarker”, “Imaging”, “Amyloid”, “CSF”, “Cognition”, “APOE”, “Genetics”, “Classification”, “Longitudinal studies”, and so on." (PMID 29095836, 2017). "However, although numerous studies document that APOE-e4 increases the relative risk of Alzheimer disease (compared to no copies of APOE-e4, there is a 2- to 4-fold increase in risk for one copy of APOE-e4, and an 8-to 15-fold increase for two copies), its effect on absolute risk is less clear." (PMID 28323826, 2017). "The peptide modulated 77 genes, of which 65 are listed in the AlzBase database and include the hallmarks of Alzheimer’s disease: APP, APOE, PSEN1, and PSEN2." (PMID 28798312, 2017). "Human studies have been dominated by evaluation of the relationship of APOE genotype with a range of diseases including CVD, Alzheimer disease, and age-related macular degeneration." (PMID 27755538, 2016). "Using qPCR, we confirmed glutamate-induced upregulation, normalized by candesartan, of a number of these genes, including several factors with fundamental roles in APP metabolism and Alzheimer’s disease, such as ADAM metallopeptidase domain 17 and APOE." (PMID 26822027, 2016).
Alzheimer disease (continued). "Therefore, it is typically recommended that the ApoE genotype, which represents the most important genetic risk factor for Alzheimer's disease, not be evaluated in asymptomatic individuals, and many physicians do not evaluate ApoE genotype even in symptomatic patients." (PMID 27294343, 2016). "ApoE plasma measurements derived from this study have been recently published and are in agreement with the findings from the North American Alzheimer's Disease Neuroimaging Initiative (ADNI), which reports an APOE genotype effect." (PMID 25012867, 2014). "Long noncoding RNA (lncRNA) within mRNA sequences of Alzheimer's disease genes, namely, APP, APOE, PSEN1, and PSEN2, has been analyzed using fractal dimension (FD) computation and correlation analysis." (PMID 23662159, 2013). "The long noncoding RNAs (lncRNAs) within the mRNA sequences in Alzheimer's disease genes, namely, APP, APOE, PSEN1, and PSEN2, have been analyzed in terms of fractal dimension computation and correlation analysis." (PMID 23662159, 2013). "In contrast to EOFAD, several risk genes such as apolipoprotein E (APOE), EPHA1, CD33 and MS 4A 6A are involved in the pathogenesis and development of late-onset Alzheimer’s disease (LOAD), in which APOE is the most notable." (PMID 23700427, 2013). "In our study the APOE gene maps to a single pathway, the KEGG Alzheimer's disease pathway, and this pathway is selected in ≈ 13 % of subsamples." (PMID 22982105, 2012). "This was observed in an analysis of late-onset Alzheimer's disease, when all possible 2 and 3-locus MDR and MDR-PDT models that included APOE were significant according to the permutation test." (PMID 20186329, 2010). "Moreover, APOE may be involved in Alzheimer's disease through a tau pathway." (PMID 16603077, 2006). "Moreover, genetic loci relevant to Alzheimer’s disease, such as PICALM and APOE, appear to converge with PD pathophysiological networks." (PMID 40178685, 2025). "For example, in Aymara and Quechua populations, global Native American ancestry (NA) has shown a protective effect against Alzheimer’s disease and related disorders among APOE-ε4 non-carriers." (PMID 41440103, 2025). "However, the consequences of the reported molecular-level connection between ApoE and HSV1 infection on the development of Alzheimer’s disease remain elusive." (PMID 40295730, 2025). "Other research in Alzheimer’s Disease Neuroimaging Initiative participants has reported accelerated cognitive decline and increased medial temporal volume loss with high BPV in ApoE ɛ4 carriers, but did not examine sex-based differences." (PMID 41109864, 2025). "Positive associations between HRT use, allocentric processing, and hippocampal volume were only observed in APOE ε4 carriers and not in APOE ε4 non‐carriers (mean age 65.1 years) in the European Prevention of Alzheimer's Dementia Longitudinal Cohort Study." (PMID 41263327, 2025). "Among non-carriers of the APOE ε4 allele, compared to those with low PRS and high PA, participants with low PRS and low PA had a significantly increased risk of Alzheimer’s disease (HR 1.940, 95% CI 1.081–3.479)." (PMID 41329349, 2025). "We identified 14 Alzheimer’s disease-related genes that were expressed in the prefrontal cortex (e.g., APP and APOE) and 55 RIKEN bioresources, which were genetically modified mice related to these genes, predicted to be relevant to Alzheimer’s disease research." (PMID 40380154, 2025). "Furthermore, APOE genotyping has been shown to influence the clinical expression and, potentially, the radiological phenotype of PSEN-1-related Alzheimer's disease." (PMID 41283076, 2025). "One could imagine that this is the case for APOE, since APOE4 individuals generally die prematurely of Alzheimer’s disease." (PMID 40497443, 2025). "Indeed, an unusual relationship between iron, APOE genotype and cognitive decline was reported in MCI and AD subjects from the Alzheimer Disease Neuroimaging Initiative (ADNI) cohort." (PMID 40275327, 2025).
Alzheimer disease (continued). "Eight (57.1%) Alzheimer's disease patients were APOE ɛ4 carriers, with no significance difference between EAD and NEAD groups (P = 0.62, Fisher's exact test)." (PMID 39949405, 2025). "Using data from the European Prevention of Alzheimer's Dementia (EPAD) cohort, the study found that APOE ε4 carriers who used HRT had improved delayed memory performance and larger brain volumes, specifically in the entorhinal cortex and amygdala, compared to non-users and non-carriers." (PMID 39886338, 2024). "Nonetheless, the study provides compelling evidence that APOE-ɛ4 and AD-PRS independently and additively influence longitudinal trajectories of neurodegeneration in Alzheimer's disease-sensitive regions and synergistically increase WMH accumulation among cognitively normal individuals." (PMID 39229494, 2024). "Next, we assessed the transcriptome of genes of interest to Alzheimer’s disease and resistance, APOE, APP, MAPT, PSEN1, and RELN and found no notable differences across cell lines." (PMID 38571814, 2024). "This discrepancy is unusual and unexpected even given the patients’ APOE genotype status and shorter disease duration than if they had pure Alzheimer’s disease without MSA." (PMID 38712319, 2024). "First, the atrophy rates in a composite volume measure of Alzheimer's disease-vulnerable regions (SPARE-AD) and the hippocampus demonstrated an APOE-ɛ4 gene-dose effect, with greatest atrophy among ɛ4 homozygous participants, followed by ɛ4 heterozygous participants, and least among ɛ4 non-carriers." (PMID 39229494, 2024). "In order to establish whether our vertex-wise findings reflect the ‘penumbra’ of subsequent atrophy, longitudinal studies comprising a wider spectrum of cognitively normal APOE ɛ4 carriers, individuals with MCI and Alzheimer’s disease are warranted." (PMID 38384997, 2024). "With respect to APOE ε4 homozygosity, the AD-PRS was significantly higher in individuals with young-onset Alzheimer’s disease (onset before 65 years old) compared to individuals who were cognitively unimpaired and older than 75 years (OR = 8.39 [2.0–35.2], p = 0.003)." (PMID 38279230, 2024). "While conclusions are limited due to the cross-sectional design, our findings imply that APOE ɛ4-related changes in ODI may precede macroscopically visible changes in cortical atrophy and may be a more sensitive marker of incipient Alzheimer’s disease." (PMID 38384997, 2024). "Increasing serum glucose levels were significantly associated with declines in rCMRgl in key brain regions affected by Alzheimer’s disease, independent of APOE ε4 status." (PMID 39659303, 2024). "In Alzheimer's disease (AD), characterized by the presence of amyloid-beta (Aβ) plaques and tau protein tangles, critical genetic factors include the amyloid precursor protein (APP), presenilin 1 (PSEN1), presenilin 2 (PSEN2), and apolipoprotein E (APOE)." (PMID 39411638, 2024). "The accuracy of the new model with features selected from a combination of the RS, Alzheimer’s Disease Assessment Scale (ADAS) and apolipoprotein E (APOE4), achieved an AUC of 0.867, higher than that achieved for a RS model alone (0.828), or using the ADAS (0.720) and APOE4 (0.591) alone." (PMID 37682491, 2023). "This binding may be similar to what has been described in the context of Alzheimer’s disease, where TREM2 in microglia binds to amyloid-β–lipoprotein complexes via APOE, thereby preventing amyloid-β accumulation." (PMID 36766683, 2023). "Our findings interestingly show a strong association between polygenic risk of type 2 diabetes, as well as clinical type 2 diabetes, and vascular dementia, although not Alzheimer’s disease, in non-carriers of APOE ε4." (PMID 37091584, 2023). "Furthermore, observational studies investigating effect moderation by APOE genotype have indicated that higher levels of physical activity might help attenuating both cognitive deficits and risk for Alzheimer’s disease more so in carriers than in non-carriers of the ApoE-ε4 allele." (PMID 36631905, 2023).